HIF1A (hypoxia inducible factor 1 subunit alpha)
Diseases named in the same sentence as HIF1A in open-access papers (continued):
Sharing a sentence is not in itself a finding about the gene and the disease.
tumor (continued). "Notably, elevated HIF1α levels are strongly correlated with aggressive tumor characteristics such as metastasis, angiogenesis, and resistance to therapy, reflecting its role in the transcriptional regulation of genes crucial for adaptation to hypoxic TME." (PMID 39697237, 2024). "Using lysosomal inhibitors can rescue lysosomal expression of HIF1a in epithelial tumor cells." (PMID 38370407, 2024). "Moreover, immunofluorescence staining of tumor tissues revealed lower expression of HIF-1α in the PEDF-H- and the P-EV-treated groups than controls at both 15 and 18-d time points, demonstrating their significantly reduced intratumoral hypoxia." (PMID 39355307, 2024). "Moreover, in compliance with restored IFN-γ production in Hif1α–/– T cells treated with NaAc, their tumor-killing capacity was restored as well." (PMID 39477954, 2024). "Third, the rapid proliferation of tumor cells generates a hypoxic internal microenvironment, which stabilizes hypoxia-inducible factor 1 alpha (HIF-1α), further enhancing glycolytic activity and inhibiting oxidative phosphorylation (OXPHOS) under low oxygen conditions." (PMID 39610917, 2024). "However, while FDFT1 acts as a tumor suppressor by negatively regulating AKT/mTOR/HIF1α signaling in CRC cells, SQLE activates the β‐catenin oncogenic pathway." (PMID 38517197, 2024). "HIF-1α (Hypoxia-Inducible Factor 1-alpha) typically requires the coactivator p300 to drive the expression of its target genes under hypoxic conditions, which promote tumor survival." (PMID 39273204, 2024). "Due to the inversion of the HIF-1α/HIF-2α expression ratios in the peritumor samples, we could categorize this phenotype as being more shifted towards an “HIF switch” in contrast to the tumor phenotype dominated by HIF-1α." (PMID 38607072, 2024). "Thus, it has been found that the use of HIF-1α inhibitors in conjunction with cancer vaccines will result in better tumor recognition and destruction by the immune system." (PMID 39493156, 2024). "Therefore, this study assessed the expression of FAK, ILK, CD44, HIF-1α, and Ki67 in EC patients after neoadjuvant radiochemotherapy followed by tumor resection (NRCHT+R) and correlated these markers with the MTE." (PMID 38727811, 2024). "Whilethe relative contribution of each isoform to the survival and growthof tumors is dependent on multiple factors, including tumor type andstage of tumor, there is significant clinical evidence linking elevatedlevels of both HIF-1α and HIF-2α to poor patient outcomesin a wide variety of cancers." (PMID 38503564, 2024). "Furthermore, the two scaffolds significantly upregulated the gene expression levels of NOTC-1, HIF-1α, and IL-6 that are involved in the signaling cascade between CSCs and the tumor stem niche, promoting resistance and metastasis." (PMID 38791452, 2024). "Following our confirmation of the impact of PHD2/3 on T-cell activation, our investigation extended to determining whether stabilizing HIF-1α through deletion of PHD2/3 in CD8 T cells would enhance their anti-tumor function in other tumor models." (PMID 39242595, 2024). "However, tumor cells continue to grow in hypoxic environments due to HIF-1α-regulated metabolic reprograming." (PMID 38542288, 2024). "However, the HIF-1α correlated more on the basis of VEGF in the endothelium of the tumor angiogenesis." (PMID 38313904, 2024). "PDT might improve the clinical response of ICIs by upregulating tumor HIF-1α and PD-L1 expressions in NSCLC." (PMID 38609977, 2024). "This suggests a combinational therapeutic approach in which combining HIF-1α inhibitors with PD-L1 blockade could abrogate tumor hypoxia and enhance the immune system in individuals with cancer." (PMID 38612546, 2024). "Since IGFBP5 is reported as a direct transcriptional target of HIF1α, it may serve as a feedback mechanism for tumours to inhibit IGF1R signalling in adjacent normal cells." (PMID 38886900, 2024).
tumor (continued). "Additionally, tumor tissue pO2 levels were directly measured before and after treatment, and immunohistochemical staining was employed to observe HIF-1α in tumor tissue." (PMID 39872052, 2024). "Several other reports have revealed that hypoxia in the TME might induce T-cell exhaustion in mice, and deprivation of hypoxia-inducible factor-1 alpha (HIF-1α) could increase NK cell activity and infiltration in tumor areas." (PMID 38500661, 2024). "Under normal culture conditions, the overexpression or activation of IDH1 had an inhibitory effect on tumor cells, which may be related to the regulation of HIF1a stability by IDH1." (PMID 38622131, 2024). "HIF‐1α inhibition reduced glutamine consumption in tumour cells." (PMID 38506093, 2024). "The expression levels of Epas1 and Vegf mRNA in the tumor tissue of the TH mice were lower in comparison with the control group, while the levels of Hif1a, Epas1, and Hif3a mRNA expression in the peritumoral area were statistically significantly higher relative to the tumor tissue." (PMID 39063041, 2024). "Likewise, functional experiments confirmed that USP21 promoted tumor growth in a HIF1A-dependent manner." (PMID 38385089, 2024). "This question could be answered more fully by using archival tumour samples from previous [18F]FMISO trials to assess correlation with HIF1α or CaIX." (PMID 39286295, 2024). "HIF-1α οverexpression was found in IDH-wild-type tumor sites." (PMID 39055895, 2024). "PDK1 regulation by HIF-1α promotes tumor glycolysis and malignant progression." (PMID 38671369, 2024). "Consequently, HIF-1α expression is up-regulated in tumor cells following activation of the PI3K/AKT pathway." (PMID 38771435, 2024). "The SMAD-specific E3 ubiquitin protein ligase 2 (SMURF2) has emerged as a critical regulator in cancer biology, modulating the stability of Hypoxia-Inducible Factor 1-alpha (HIF1α) and influencing a network of hypoxia-driven pathways within the tumor microenvironment (TME)." (PMID 39697237, 2024). "After the treatments of IR‐TAM@Alb, the expression of HIF‐1α mRNA and HIF‐1α protein was decreased, meaning that the hypoxia tumor microenvironment may be remissed by IR‐TAM@Alb treatment." (PMID 38715382, 2024). "Antiangiogenic therapies result in vascular regression and can increase intra-tumoral hypoxia levels, leading to an abnormal upregulation of HIF1-α that can stimulate tumor and stromal cells to secrete large amounts of angiogenic factors, such as FGF and ANGPT2." (PMID 38727322, 2024). "The link between PAQR6 and hypoxia-induced factors such as HIF1A suggests that it may act downstream of hypoxia-regulated pathways, integrating immune suppression and angiogenesis in the tumor microenvironment." (PMID 39742277, 2024). "In addition, As2O3 treatment in vitro and in vivo resulted in dose-dependent decreased expression of HIF-1α, and Dll4-Notch pathway that are involved in the regulation of tumor angiogenesis." (PMID 39717738, 2024). "In addition, the overexpression of HIF-1α in tumor cells leads to metabolic reprogramming, resulting in the Warburg effect, which results in the production of large amounts of lactate." (PMID 39660139, 2024). "In addition, tumor size > 4 cm (HR = 1.10, 95 % CI 1.00‒1.32, p = 0.012) and HIF-1α with YKL-40 serum level above the cut-off value (HR=1.49, 95 % CI 1.30‒1.91, p = 0.001) were also independent prognostic factors for FTC." (PMID 39277981, 2024). "Mir-210 is overexpressed in the tumor tissue but does not show a well-established association with any of the main proangiogenic genes, including HIF-1α." (PMID 38607072, 2024).
tumor (continued). "Therefore, new therapeutic strategies targeting hypoxic tumor microenvironments, including HIF-1α inhibitors, hypoxia relief, oxygen sensitive therapy, etc., have clinical application potential of CM." (PMID 38364250, 2024). "LINK-A’s activation of HIF1α signaling may contribute to an immunosuppressive tumor microenvironment, challenging the immune system’s ability to mount an effective antitumor response." (PMID 38645412, 2024). "Therefore, HIF-1α activation promotes the proliferation and enrichment of tumor stem cells, contributing to drug resistance." (PMID 38799423, 2024). "In hypoxia, for instance, hypoxia enhances the secretion of CCL28 by tumor cells in a HIF-1α-dependent mode, which enhances the recruitment of CCR10+ T reg cells to the tumor site, thus inhibiting the functions of cytotoxic T cells and accelerating tumor growth." (PMID 38165484, 2024). "In solid tumors, tumor cells frequently experience hypoxia, leading to the lack of oxygen-dependent hydroxylation and proteasomal degradation of hypoxia-inducible factor 1-alpha (HIF-1α), which causes its accumulation." (PMID 39385213, 2024). "S12C), we asked whether knocking out HIF1A would result in enhanced cytotoxicity of tumor cells in our experimental system." (PMID 39475618, 2024). "HIF-1α-NKKO mice engrafted with colon cancer cells (MC38) or LLC showed decreased tumor growth, even as assessed by an increase in cell death (caspase-3 staining), accompanied by a reduction in pericyte coverage and an increase in Glut-1, which correlates with the hypoxic state." (PMID 39086395, 2024). "In this regard, HIF-1α can synergistically promote radio resistance and induce tumor progression." (PMID 38474362, 2024). "In addition, HIF-1α-dependent upregulation of the immunosuppressive ligand PD-L1 on tumor cells contributes to cancer immune escape." (PMID 38175205, 2024). "HIF1-α is responsible for the upregulation of immunomodulatory surface ligands like cytotoxic T-lymphocyte-associated protein 4 (CTLA-4) and programmed death ligand 1 (PD-L1), causing the inhibition of the anti-tumor immune responses." (PMID 39409094, 2024). "Notably, HCC patients with high CSC levels exhibited an accumulation of SPP1+ macrophages (Macro_SPP1) expressing metalloproteinases (MMP9, MMP12, and MMP7) regulated by HIF1A, suggesting a hypoxic tumor region connecting Macro_SPP1 and CSC." (PMID 38521868, 2024). "HIF-1α expression in immune cells, but not tumor cells, was significantly associated with a higher histologic grade." (PMID 39202223, 2024). "Previously, we showed that Salmonella could reduce hypoxia-inducible factor-1 α (HIF-1α) expression and may improve the hypoxic condition in the tumor microenvironment and increase the radiation or chemotherapy effects 20-22." (PMID 38356700, 2024). "Interestingly, HIF-1α and HIF-2α protein levels can also be increased in cancer cells due to loss of function of different tumor suppressors, including VHL, which results in either increased HIF-1α synthesis or decreased HIF-1α degradation." (PMID 39078527, 2024). "Due to the central role of immunotherapy in the investigation of cancer treatment, further investigation including research strategies of modulation of the immune tumor microenvironment, such as the GBM-associated and hypoxia-induced HIF-1α/VEGF pathways would contribute to the treatment of GBM." (PMID 39055895, 2024). "The co-delivery of VEGF siRNA and PEITC could achieve precise silencing of VEGF, inhibit the accumulation of HIF-1α under hypoxic conditions, and induce apoptosis in tumor cells." (PMID 38584690, 2024). "Notably, this degradation process operates independently of the von Hippel-Lindau (VHL) protein, providing an alternative pathway for controlling HIF1α levels in tumor cells." (PMID 39697237, 2024). "Hypoxia and HIF-1α impose various physical and metabolic challenges that favor a tumor immunosuppressive environment that could also be supported by the TNFR2 signaling pathway." (PMID 39609700, 2024).
tumor (continued). "In vivo experiments showed that PDT could inhibit tumor growth and upregulate HIF-1α and PD-L1 expressions in NSCLC tissues with a positive correlation, which might influence the blocking activity of ICIs on the HIF-1, and PD-L1-related signaling pathways." (PMID 38609977, 2024). "Previous studies have indicated that the HIF-1α in the tumor microenvironment promotes the expression of VEGF, HGF, met proton genes, and induces the degradation of extracellular matrix, which is involved in the mechanism of cancer cell metastasis known as EMT." (PMID 38689341, 2024). "Similarly, the intratumoral injection of Neospora caninum tachyzoites in mice bearing B16.F10 melanoma tumors displayed a trend towards elevated HIF-1α gene expression in the tumor site." (PMID 39120310, 2024). "This suggests that enhancing SMURF2 activity could be a viable strategy to mitigate the effects of HIF1α-driven tumor progression, particularly in hypoxia-adapted tumors." (PMID 39697237, 2024). "For example, there could be a greater impact on genes regulated by VDR related to angiogenesis, invasion, and metastasis (e.g., HIF1α and IL-8) compared with genes that influence tumor initiation (i.e., malignant transformation) (e.g. MYC and RB)." (PMID 39705237, 2024). "Because MAOA and MAOB functioned in dopamine degradation, we hypothesized that elevated HIF-1A might decrease the dopamine in MES-like high tumor." (PMID 36720864, 2023). "In the present study, we found that DOKD may exert its role in inhibiting CT26+ tumor angiogenesis by inhibiting the STAT3/HIF-1α/VEGFA pathway." (PMID 37239383, 2023). "The HIF-1α level in the tumor tissue was significantly lower in the AsA ( +) group than in the AsA (−) group but higher in the AsA + HIF-1α-ac group than in the AsA ( +) group, suggesting that DMOG reversed the decrease in HIF-1α level in the IP + LC model administered AsA." (PMID 38012636, 2023). "Enriched canonical pathway terms that support the hypothesis that the MDM-B cluster is pro-angiogenic include glycolysis I (z-score of 2.45), tumor microenvironment (z-score of 3.16), and hypoxia inducible factor 1α (HIF1α, z-score of 2.83) signaling pathways." (PMID 37858232, 2023). "Neutrophil-specific deletion of HIF-1α significantly reduced tumor burden and converted the tumor-infiltrating neutrophil from a pro-tumorigenic to an anti-tumorigenic phenotype, which was accompanied by increased numbers and activity of activated NK cells and CTLs." (PMID 36614196, 2023). "We showed increased expression of HIF-1α is a tumor-specific finding." (PMID 36766555, 2023). "We also conducted qPCR to determine ALKBH5 and HIF-1α mRNA expression levels in tumor samples." (PMID 36632222, 2023). "In addition, in a murine model of breast cancer, it was shown that the ablation of macrophage HIF-1α diminished macrophage-dependent T cell suppression and led to reduced tumor growth." (PMID 36901858, 2023). "A study demonstrated that the Erk1/2/HIF-1α signaling pathway might promote the angiogenesis of tumor cells by activating VEGFA." (PMID 37239383, 2023). "Many studies have demonstrated that glycolysis is involved in the activation of oncogenes, such as phosphatidylinositol 3-kinase (PI3K) and hypoxia-inducible factor-1 alpha (HIF-1α) in the tumor microenvironment (TME), and acts as an energetic source for cancer cells." (PMID 37853445, 2023). "Also, our study reports the first assessment of [68Ga]Ga-FAPI PET imaging as a surrogate biomarker of tumor hypoxia using immunohistochemical staining for HIF-1α for correlation in a prospectively recruited study population." (PMID 37568769, 2023). "Thus, the AREG/EGFR/HIF-1α signaling pathway contributes to Th9 cell differentiation and anti-tumor function." (PMID 36154925, 2023).
tumor (continued). "The expression of hypoxia-inducible factor 1-alpha (HIF-1α) was detected in tumor tissues and adjacent normal tissues from 29 patients with OSCC using reverse transcription quantitative real-time polymerase chain reaction (qRT-PCR), western blotting, and immunohistochemistry (IHC)." (PMID 37095487, 2023). "HIF-1α and Lox were also regulated mutually to promote tumor cells growth." (PMID 38031108, 2023). "Hypoxic microenvironments created by the rapid growth of tumor cells can promote HIF-1α expression." (PMID 37864196, 2023). "During tumor development, HIF-1α is pivotal to the cells’ metabolic adaptation to their surroundings, as growth success under metabolic duress strongly depends upon the cell’s ability to shift from oxidative phosphorylation (OXPHOS) to the more inefficient glycolytic metabolism for ATP generation." (PMID 36874131, 2023). "Thus, previous works have shown that the hypoxic selectivity of compounds 26c, 64a,d, and 99b is associated with the inhibition of expression and activity of the hypoxia-induced factor HIF-1α in tumor cells." (PMID 37631089, 2023). "Activated hypoxia-inducible factor-1 alpha (HIF-1α) is a pivotal molecule in these adaptation mechanisms as it activates the transcription of more than 100 downstream genes that regulate vital biological processes for tumor survival and progression." (PMID 38140111, 2023). "Furthermore, we described the mechanism by which IL-6 mediates tumor immunosuppression by focusing on metabolic competition between T-cells and tumor cells via hypoxia-pseudohypoxia-mediated HIF1α activation." (PMID 36764954, 2023). "Once in the nucleus, HIF-1α functions as a transcription factor, influencing the regulation of various target genes involved in metabolism, inflammation, vascular homeostasis, and tumor formation." (PMID 37894443, 2023). "Furthermore, the inhibition of mTOR downstream of AKT with rapamycin significantly reduced HIF-1α activity and tumor growth." (PMID 36901857, 2023). "GSE33630 data further confirmed the HIF1A overexpression in the tumor tissue (P < 0.001)." (PMID 36994412, 2023). "CDK1 stabilizes HIF1A through direct phosphorylation of Ser668 to promote tumor growth." (PMID 37311884, 2023). "Cardamonin protected the heart from oxidative damage and inflammatory injury by activating Nrf2-related cytoprotective system in cardiac muscle cells, whereas cardamonin suppressed tumor cell growth by inducing oxidative stress through NF-κB/mTOR and HIF-1α pathways." (PMID 37304865, 2023). "Additionally, we found that the density of PHD3 and RP58 decreased with increasing tumor grades, while the expression of HIF‐1α, VEGF, and GLUT1 showed an opposite trend." (PMID 37701531, 2023). "Moreover, Glycogen Synthase Kinase-3 (GSK-3) mediates a sequence of substrates such as c-MYC and HIF-1α to induce cell growth and tumor development." (PMID 37895941, 2023). "Tumor hypoxia and activation of HIF-1α may also block ferroptosis by reducing PUFA via increased intracellular lipid droplet storage." (PMID 37568677, 2023). "Its related study mechanism confirms that SIRT3 may inhibit tumor cell progression via the ROS-FPR1/HIF-1α axis." (PMID 37747648, 2023). "While HIF2A is almost invariably overexpressed in ccRCC samples, tumor microarray studies have confirmed that up to 40% of ccRCC is unable to produce HIF1A due to deletions of the HIF1A gene situated in the 14q region in combination with inactivating mutations." (PMID 37489462, 2023). "Notably it has recently been proposed that high expression of HIF-1α in EC tissues also enhances the anti-pyroptosis characteristics of tumour cells." (PMID 37965452, 2023). "Targeting this process may have therapeutic potential, as mice bearing an NK-specific deletion of VEGF or HIF-1α exhibit reduced growth of solid tumors and impaired tumor vascularization." (PMID 36980629, 2023). "Hypoxia and HIF1α can induce tumor cells to become resistant to cytotoxic T cells." (PMID 37143325, 2023).